CSPP1 (centrosome and spindle pole associated protein 1)
Description:
May play a role in cell-cycle-dependent microtubule organization.
Synonyms: CSPP; FLJ22490; JBTS21; CSPP-L
Tractability: PROTAC: ubiquitination databases record sites on it.
Gene: Protein-coding gene on chromosome 8 (67,062,381 to 67,196,778, forward strand). Ensembl gene ENSG00000104218.
Subcellular location: Cytoplasm, cytoskeleton, microtubule organizing center, centrosome; Cytoplasm, cytoskeleton, spindle; Cytoplasm, cytoskeleton, spindle pole; Cell projection, cilium
Subcellular location (Human Protein Atlas): Basal body; Centriolar satellite; Centrosome; Primary cilium; Vesicles
Gene Ontology:
Molecular function: identical protein binding; protein binding
Biological process: positive regulation of cell division; positive regulation of cytokinesis
Cellular component: centrosome; cilium; spindle; spindle pole; microtubule
Genetic constraint (gnomAD): Loss-of-function variants: 40 observed, 59.42 expected, observed/expected ratio (o/e) 0.67, 90% interval 0.52 to 0.88. The upper end of that interval is the gene's LOEUF score, 0.88, which puts it in group 3 of 6, group 1 being the genes least tolerant of losing a copy. Missense variants: 646 observed, 699.31 expected, observed/expected ratio (o/e) 0.92, 90% interval 0.87 to 0.99. Synonymous variants: 223 observed, 242.61 expected, observed/expected ratio (o/e) 0.92, 90% interval 0.82 to 1.03.
Gene-disease validity (ClinGen):
ClinGen rates the evidence that CSPP1 causes each of these diseases.
Joubert syndrome 21 (autosomal recessive): Definitive.
Homologues: Orthologues: chimpanzee CSPP1 (96% identical), macaque CSPP1 (95% identical), pig CSPP1 (87% identical), dog CSPP1 (87% identical), rabbit CSPP1 (85% identical), mouse Cspp1 (77% identical), rat Cspp1 (77% identical), tropical clawed frog cspp1 (51% identical), zebrafish cspp1a (37% identical), zebrafish cspp1b (21% identical).
Diseases named in the same sentence as CSPP1 in open-access papers:
CSPP1 is named in the same sentence as 37 diseases in open-access papers, as found by Europe PMC text mining. Sharing a sentence is not in itself a finding about the gene and the disease. The quoted sentences say what the papers report.
Joubert syndrome (14 papers, 2015 to 2025). Joubert syndrome (JS) is characterized by congenital malformation of the brainstem and agenesis or hypoplasia of the cerebellar vermis leading to an abnormal respiratory pattern, nystagmus, hypotonia, ataxia, and delay in achieving motor milestones. "Here, we used in vitro reconstitution assays to investigate microtubule-stabilizing properties of CSPP1, a centrosome and cilia-associated protein mutated in the neurodevelopmental ciliopathy Joubert syndrome." (PMID 36752787, 2023). "These cytoskeleton buffers proved useful for studying CSPP1 when in 2014, three laboratories published papers that showed CSPP1 was a causative gene for Joubert syndrome (a neurodevelopmental ciliopathy)." (PMID 28352462, 2017). "Deleterious mutations of the Centrosome/Spindle Pole associated Protein 1 gene, CSPP1, are causative for Joubert-syndrome and Joubert-related developmental disorders." (PMID 26241740, 2015). "Mutations in the CSPP1 gene have been shown to cause a developmental brain disorder called Joubert syndrome, and CSPP1 was found to be involved in neural-specific functions of primary cilia." (PMID 26541409, 2015). "Causative biallelic CSPP1 variants have been implicated in Joubert syndrome (MIM:615636)." (PMID 37035737, 2023). "Mutations in Cspp1 have also been linked to Joubert syndrome, a developmental brain disorder." (PMID 34064652, 2021). "Finally, mutations in CSPP1 are a major cause of Joubert-syndrome and Joubert-related disease—ciliopathies in which affected individuals frequently present with renal and hepatic cysts." (PMID 26241740, 2015). "Mutations in genes encoding CSPP1 and its ciliary binding partners lead to defects in ciliogenesis and result in a range of ciliopathies, such as the neurodevelopmental disorder known as Joubert syndrome, or the more severe Meckel-Gruber syndrome with multiple developmental abnormalities." (PMID 36752787, 2023). "These genes are associated with skeletal dysplasias, including progressive pseudorheumatoid dysplasia (WISP3), Joubert syndrome and ciliopathies (CSPP1), mucolipidosis types II/III (GNPTAB), and Larsen syndrome or other spondyloepiphyseal dysplasias (FLNB)." (PMID 40428312, 2025). "Several PSGs are associated with Joubert syndrome, including AHI1, CSPP1, and TCTN1, and are essential for cerebellar development." (PMID 33441416, 2021). "Some reports documented that a CSPP1mutation is the main cause of Joubert syndrome (JBTS), a type of invisible cilia and Jeune asphyxiating thoracic dystrophy (JATD), whereas overexpression of CSPP1 in hTERT-RPE cells can result in longer cilia." (PMID 31651332, 2019). "Disruptive mutations in Centrosome/Spindle Pole associated Protein 1 (CSPP1, JBTS21) were recently identified to be a major cause for Joubert syndrome." (PMID 26241740, 2015). "Here we reconstituted in vitro the individual and collective activities of the ciliary tip module proteins CEP104, CSPP1, TOGARAM1, ARMC9 and CCDC66, which interact with each other and with microtubules and, when mutated in humans, cause ciliopathies such as Joubert syndrome." (PMID 39856351, 2025). "Moreover, CCDC66 is part of a ciliary tip module that includes other MAPs such as CEP104, CSPP1, TOGARAM1 and ARMC9, which are mutated in the Joubert syndrome." (PMID 40729374, 2025). "Moreover, the interactome contained components of the CCDC66-linked Joubert syndrome module, such as ARMC9, TOGARAM1, CEP104 and CSPP1, known for their roles in cilium length regulation." (PMID 40729374, 2025). "Indeed, RAG1 is involved in a severe spectrum of immunodeficiencies that can only be detected after birth (MIM:601457), while CSPP1 is involved in Joubert syndrome (MIM:615636) for which prenatal signs cannot be detected by US at early stages." (PMID 37035737, 2023).
Joubert syndrome (continued). "Interestingly, five of the potential interactors (PIBF1, CSPP1, OFD1, C2CD3, and KIF7) have been linked to a single ciliopathy, the Joubert syndrome, reinforcing the role of CCP6 activity in cilia regulation." (PMID 36674791, 2023). "Intriguingly, five of the candidate interactors found in our BioID-based interactomic study (i.e., C2CD3, PIBF1, CSPP1, OFD1, and KIF7) are related to a single rare pathology, the Joubert syndrome." (PMID 36674791, 2023).
ciliopathy (9 papers, 2015 to 2025). A genetic disorder of the cellular cilia or the cilia anchoring structures, the basal bodies, or of ciliary function. "Very recently, we and others have shown that mutations in CSPP1, a gene encoding a core centriolar protein, can underlie a range of ciliopathy phenotype including JATD." (PMID 25361962, 2015). "Loss-of-function mutations of CSPP1 lead to ciliopathies, including Joubert syndrome." (PMID 38772741, 2024). "Considering the crucial role of CSPP1 in ciliopathies, investigating its cellular activity and understanding its physiological implications hold great promise." (PMID 38772741, 2024). "Furthermore, the similarity between the activities of CSPP1 and MT-stabilizing agents raises an interesting possibility that the absence of CSPP1 or its binding partners might be compensated by such compounds, suggesting potential avenues for pharmacological intervention in ciliopathies." (PMID 36752787, 2023).
breast carcinoma (2 papers, 2015 to 2021). "CircCSPP1 ((hsa_circ_0001806), derived from centrosome and spindle pole associated protein 1 (CSPP1), acts as an oncogene in luminal breast cancer and human B-cell lymphoma." (PMID 33663510, 2021).
colon carcinoma (2 papers, 2015 to 2022). "A novel circRNA back-splicing 8–11 exons of the CSPP1 gene, termed circCSPP1, was found, which plays a tumor-promoting role in colon cancer." (PMID 35101080, 2022).
colorectal cancer (2 papers, 2020 to 2021). A primary or metastatic malignant neoplasm that affects the colon or rectum. "In the present study, we investigated the mRNA level and the promoting effect of circRNA CSPP1 (circCSPP1) in colorectal carcinoma liver metastasis." (PMID 32612946, 2020).
hepatocellular carcinoma (2 papers, 2020 to 2021). A malignant tumor that arises from hepatocytes. "Several recent studies have reported the oncogenic role of circ-CSPP1 in ovarian cancer, cervical cancer, glioma, and hepatocellular carcinoma." (PMID 34124372, 2021).
Obesity (2 papers, 2019 to 2021). Accumulation of substantial excess body fat. "Furthermore, Western blot analysis verified that low CSPP1 expression accompanies obesity-associated human astheno-teratozoospermia." (PMID 31651332, 2019). "Obesity is associated with declines in the abundances of CETN1 and CSPP1 and affect sperm morphology in mice and relevant clinical samples." (PMID 34330296, 2021). "Obesity is associated with declines in the CETN1 and CSPP1 abundance and compromise of both sperm morphology in mice and relevant clinical samples." (PMID 31651332, 2019). "Even though the function of CENT1 is known in spermatogenesis, there is scant information regarding the role of CSPP1 and CETN1 in obesity associated teratozoospermia." (PMID 31651332, 2019). "The results show that the declines in centrosome and spindle pole associated protein 1 (CSPP1) and Centrin 1 (CETN1) expression levels in mice fed a HFD may contribute to obesity-induced male subfertility." (PMID 31651332, 2019). "Taken together, these data suggest that regionally delimited expressions of CSPP1 and CETN1 are strongly associated with spermiogenesis and maintenance of normal sperm morphology whereas its deficiency in sperm may contribute to obesity-associated asthenozoospermia and teratozoospermia." (PMID 31651332, 2019). "Additionally, immunoblot analysis showed that CSPP1 and CETN1 contents were significantly reduced in sperm from overweight or obesity males compared with that from normal males, which is in agreement with the results in the mice of HFD group." (PMID 31651332, 2019).
ovarian carcinoma (2 papers, 2021 to 2022). A malignant neoplasm originating from the surface ovarian epithelium. "Moreover, circ_100395, circFGFR3, circ_0000554, circCELSR1, circ-PTK2, circLNPEP, circ-CSPP1, circ_0000745, circ_100395 and circPLEKHM3 have been shown to regulate epithelial-mesenchymal transition and metastatic ability of ovarian cancer cells." (PMID 35488239, 2022).
acute pneumonia (1 paper, 2011). "CSPP1-E1A inhibits the ability of S. pneumoniae to acquire the rpsL streptomycin resistance gene in mouse lungs during acute pneumonia." (PMID 21909280, 2011).
cyst (1 paper, 2015). A sac-like closed membranous structure that may be empty or contain fluid or amorphous material. "Our results may suggest that cyst formation in CSPP1 could at least partially be attributed to a non-ciliary function of CSPP-L." (PMID 26241740, 2015).
developmental delay (1 paper, 2024). "This article describes a case of Joubert syndrome type 21 with microcephaly, seizures, developmental delay and language regression, caused by a CSPP1 gene variant and examines the contributing variables." (PMID 38586154, 2024).
Jeune syndrome (1 paper, 2015). Jeune syndrome, also called asphyxiating thoracic dystrophy, is a short-rib dysplasia characterized by a narrow thorax, short limbs and radiological skeletal abnormalities including "trident" aspect of the acetabula and metaphyseal changes. "Further, mutations in CSPP1 (MIM 611654) have been recently identified in individuals with Jeune Syndrome and Joubert phenotype." (PMID 25361962, 2015).
leukemia (1 paper, 2016). A malignant (clonal) hematologic disorder, involving hematopoietic stem cells and characterized by the presence of primitive or atypical myeloid or lymphoid cells in the bone marrow and the blood. "In addition to gene mutations that are known to be involved in leukemogenesis, such as ones in MYC and KRAS, we also identified mutations within PTPN21, TBX21, USP54, USP11, NCOR2, CSPP1 that have never before been identified in human leukemia." (PMID 26527318, 2016).
prostate carcinoma (1 paper, 2021). A carcinoma that arises from epithelial cells of the prostate gland. "Despite previous studies indicating that the inhibition of CSPP/CSPPL could induce G1 phase arrest in the cell cycle and the destabilization of desmosomes, how CSPP1 functions in prostate cancer remains unclear." (PMID 34760337, 2021).
ptosis (1 paper, 2018). The drooping of the upper eyelid. "Mutation of the centrosome and spindle pole-associated factor-1 gene (CSPP1) is the most common mutation associated with individuals with JS and ptosis." (PMID 30518138, 2018). "One study of patients with CSPP1-related JS reported ptosis in 15/19 individuals with the biallelic truncating mutations; another study found bilateral ptosis in 4/6 patients with CSPP1-related JS." (PMID 30518138, 2018).
teratozoospermia (1 paper, 2019). "Meanwhile, low CSPP1 and CETN1 expression levels are associated with human astheno-teratozoospermia in clinical samples." (PMID 31651332, 2019).
tumor (7 papers, 2016 to 2024). "Furthermore, the expression of circ-CSPP1 was closely associated with the tumor node metastasis (TNM) grade, lymph node metastasis, and size of these tumors." (PMID 34124372, 2021). "CSPP1 has been identified to inhibit tumor cell migration, proliferation, formation, and invasion when it was decreased and related to PI3K/Akt signaling pathway that can reduce inflammation by downregulating the degranulation of mast cells." (PMID 35578692, 2022). "The knockdown of circ-CSPP1 attenuated cell proliferation, migration, invasion and promoted apoptosis in vitro and weakened tumor growth in vivo." (PMID 34124372, 2021). "The circ-CSPP1 expressed remarkably high in borderline and tumor tissues rather benign and cancer tissues." (PMID 31481095, 2019). "Moreover, circ-CSPP1 and LASP1 levels were remarkably downregulated and miR-431 expression was strikingly upregulated in the tumor tissues derived from the sh-circ-CSPP1-transduced SW480 cells." (PMID 34124372, 2021). "Additionally, immunohistochemistry results showed that Ki-67 and MMP9 levels were decreased in sh-circ-CSPP1-transduced SW480 tumor tissues, demonstrating the repression of circ-CSPP1 knockdown on tumor cell proliferation and metastasis." (PMID 34124372, 2021). "By contrast, the transduction of sh-circ-CSPP1 led to a significant suppression of tumor growth." (PMID 34124372, 2021). "Also, the expression level of circ-CSPP1 was performed in border line, benign, ovarian tumor tissues, and non-tumor tissues." (PMID 31481095, 2019). "We next asked whether circ-CSPP1 influenced tumor growth in vivo." (PMID 34124372, 2021). "Furthermore, the variant frequencies in the tumor of five mutations within the OXTR, TBX21, CSPP1, and PTPN21 genes ranged from 40%–50% in the primary tumor, thus suggesting the likelihood that these were present in virtually all tumor cells at the onset (heterozygosity)." (PMID 26527318, 2016). "In the current work, loss-of-function phenotypes of circ-CSPP1 uncovered that circ-CSPP1 was a positive regulator of CRC cell malignant behaviors in vitro and tumor growth in vivo." (PMID 34124372, 2021). "MiR-361-5p, which is known as a miRNA with tumor-suppressing effects, was found to be down-regulated in CC with a negative correlation with hsa_circ_CSPP1 expression, as hsa_circ_CSPP1 was considered a miR-361-5p sponge." (PMID 38341592, 2024).
cancer (6 papers, 2016 to 2026). A tumor composed of atypical neoplastic, often pleomorphic cells that invade other tissues. "Subsequent knocking down of circ-CSPP1 caused an arrest in cell growth, invasion and migration and inversely, the overexpression stimulated cancer properties." (PMID 31481095, 2019). "CSPP1 is a mitosis regulator; LGALS7 and PDE2A are overexpressed in different cancer types; LDHA encodes one of the major glycolysis enzymes." (PMID 27359056, 2016). "Thus, circ-CSPP1 sponged miR-1236-3p and attenuated its silencing effect on ZEB1, consequently stimulated EMT and cancer development." (PMID 31481095, 2019). "To observe the involvement of circ-CSPP1 in CRC development, we used qRT-PCR to determine its expression in cancer tissues and paired noncancerous tissues, which were identified by H&E staining." (PMID 34124372, 2021).
brain diseases (1 paper, 2021). "Three genes (AHI1, CSPP1, and TCTN1) in the top 10 of the PSGs associated with human brain diseases, with raw dN/dS > 2, are required for both cortical and cerebellar development in humans." (PMID 33441416, 2021).
skeletal dysplasia (1 paper, 2025). Any Mendelian diseases that affects growth and development of the skeleton. "Aside from the DYM pathogenic variant, variants of uncertain significance (VUS) were detected in WISP3, CSPP1, GNPTAB, and FLNB, genes known to be associated with skeletal dysplasias." (PMID 40428312, 2025).
CSPP1 also shares sentences with these, for which no sentence is quoted: Alzheimer disease (1 paper); asthenozoospermia (1); B-cell lymphoma (1); cervical cancer (1); glioma (1); Hepatic cysts (1); Huntington disease (1); immunodeficiencies (1); Joubert syndrome type 21 (1); Larsen syndrome (1); liver cancer (1); microcephaly (1); mucolipidosis type II (1); Parkinson disease (1); progressive pseudorheumatoid dysplasia (1); retinal diseases (1); spondyloepiphyseal dysplasia (1).